MYH9 (myosin heavy chain 9)
Diseases named in the same sentence as MYH9 in open-access papers (continued):
Sharing a sentence is not in itself a finding about the gene and the disease.
cancer (continued). "Thus, DKK4 expression in CRC cancer cells reduces the expression of β-catenin in stromal cells in cancer tissues, resulting in the transformation of fibroblasts to form stress fibre-containing fibroblasts and Vimentin+F-actin+MYH9+α-SMA+ myofibroblasts in cancer stromal tissues." (PMID 38519641, 2024). "Most signaling pathways in pan-cancer, including ACTB, FLNA, MYH9, MYH10, and TLN1, exhibited high activation levels in the epithelial-mesenchymal transition (EMT) pathway, but consistent inhibition of the cell cycle, DNA damage response, and hormone AR." (PMID 38862242, 2024). "Taken together, this study proposes that in mitigating ER stress in cancer cells, LAMC2 exerts an emergency stress-resistance response by binding to MYH9 and MYH10 to promote ER-mitochondria interaction around the nucleus." (PMID 37891404, 2024). "In conclusion, our research elucidates the mechanism of MYH9 and the p-MYH9 /USP22/HIF-1α axis in promoting cancer stemness and LR in HCC." (PMID 39300073, 2024). "The qPCR and WB detection showed that the expression of TM4SF1, cancer stem–related molecules, the NOTCH pathway–related molecules, and MYH9 in LM3-LR cells was higher than that in the control group." (PMID 37069693, 2023). "In this study, we demonstrated that MYH9 facilitates cell invasion in HNC, and it has been shown in other cancers as well." (PMID 36139430, 2022). "MYH9, a cytoskeleton-related protein capable of triggering EMT in various cancers, is one of the most abundant proteins that binds to ERLR." (PMID 33664479, 2021). "Our findings provide new insights into the role of HMGA1 and MYH9 in gliomagenesis and suggest the potential application of HMGA1 and MYH9 in cancer therapy in the future." (PMID 34887392, 2021). "Targeting MYH9 blocked HBX-induced GSK3β ubiquitination to activate the β-catenin destruction complex and suppressed cancer stemness and EMT." (PMID 32296025, 2020). "Next, we investigated the expression level of MYH9 in CRC tissues and found that MYH9 was significantly higher in the cancer tissues than in the adjacent normal tissues, which was consistent with previous results." (PMID 32413870, 2020). "Based on TCGA database and bioinformatics analyses, MYH9, β-catenin, and ubiquitin expression levels were upregulated in HCC tissues (T) compared to para-carcinoma tissues (N)." (PMID 32296025, 2020). "Since MYH9 stabilized HIF-1α and promoted LR and p-MYH9 specifically interacted with HIF-1α, we wondered whether p-MYH9 could be an effective target for reversing LR and suppressing cancer stemness." (PMID 39300073, 2024). "Increased expression of DKK4 in cancer stem cells enhanced the expression of F-actin and MYH9 in fibroblasts but did not further change the morphologies of fibroblasts and myofibroblasts." (PMID 38519641, 2024). "MYH9 encodes non-muscle myosin IIA (NMIIA), which has been extensively demonstrated to contribute to cancer progression, including cell proliferation, invasion, and metastasis." (PMID 39440063, 2024). "In addition, we showed that MYH9 and MYH10 knockdown cancer cells exhibited lower colony formation and cell viability compared to the control group cells." (PMID 37891404, 2024). "In summary, we demonstrated that MYH9 could stabilize HIF-1α and promote LR, glycolysis and cancer stemness in HCC." (PMID 39300073, 2024). "Indeed, numerous studies have provided evidence of the oncogenic roles of MYH9 and DRD4 and suggested these two genes as potential therapeutic targets in diverse cancers." (PMID 36345155, 2023). "For example, non-muscle myosin IIA (MYH9) is a ubiquitously expressed cytoplasmic myosin that regulates the actin cytoskeleton, cell migration, cell polarization, and signal transduction in cancer cells." (PMID 38001682, 2023). "According to our knowledge, no previous study has demonstrated the expression of MYH9 at the surface of cancer cells using flow cytometry." (PMID 34425650, 2021).
cancer (continued). "Consistent with the previous findings, MYH9 and β-catenin expression levels were elevated (P < 0.001 and P = 0.007, respectively), but GSK3β expression levels were decreased in HCC tissues in contrast to those in para-carcinoma tissues (P < 0.001)." (PMID 32296025, 2020). "Furthermore, it examines MYH9's regulatory interactions with non-coding RNAs and its potential applications as a therapeutic target, offering insights into strategies such as RNA interference and CRISPR-based gene editing for cancer treatment." (PMID 41953727, 2025). "Therefore, the p-MYH9 /USP22/HIF-1α axis is critical for LR and cancer stemness." (PMID 39300073, 2024). "However, in mouse head and neck squamous cell carcinoma, MYH9 can have both a cancer-promoting and cancer-inhibiting role, and no definitive consensus regarding its mechanism of action exists." (PMID 38739940, 2024). "Among Cancer Gene Census genes, 1346 events were detected in 947 different loci, with the most recurrent ones being those in CLTCL1 (24 cases), CSMD3 (21 cases), MYH9 (20 cases), ANK1 (19 cases), TPR (19 cases), MYH11 (18 cases), PTPN13 (18 cases), and POLQ (17 cases)." (PMID 33809641, 2021). "To determine whether the malignant characteristics of MYH9 found in cell invasion and radioresistance are reflected in the clinical presentation of patients with HNC, we investigated the differential expression of MYH9 in normal and cancer tissues using the TCGA-HNSC dataset." (PMID 36139430, 2022). "LUAD1 enriched for alterations in EGFR, MN1 and MYH9, LUAD2 enriched for BRCA2, while LUAD3 did not enrich for known cancer drivers." (PMID 35383171, 2022). "Taken together, these observations strongly support that MYO10, MYH9 and MYO1E play essential and non-redundant roles in the functionality of the invasion machinery in cancer." (PMID 29934580, 2018).
kidney disease (61 papers, 2009 to 2025). "APOL1 gene polymorphisms have also been more intensely associated with the risk of kidney disease previously attributed to MYH9." (PMID 29862302, 2018). "MYH9-RD is characterized by congenital macrothrombocytopeniaassociated with variable degrees of sensorineural hearing loss, pre-senile cataract,and renal disease." (PMID 29782633, 2018). "Sequence variants in MYH9 encoding myosin heavy chain 2A have been associated with two forms of kidney disease." (PMID 23874454, 2013). "MYH9 was recently identified as renal susceptibility gene (OR 3–8, p<10−8) for major forms of kidney disease disproportionately affecting individuals of African descent." (PMID 20634883, 2010). "All of the MYH9 single nucleotide polymorphisms (SNPs) most strongly associated with kidney disease fall within this extended block." (PMID 20634883, 2010). "Here, we aimed to understand the cell autonomous role for MYH9&10 proteins in facilitating a specialized organelle trafficking pathway within TAL cells and to test whether loss of MYH9&10-mediated TAL cargo trafficking is sufficient to drive kidney disease." (PMID 39500539, 2025). "Thus, the presence of floxed Myh9&10 alleles and the Umod+/CreERT2 transgene together are required for development of the observed kidney disease." (PMID 39500539, 2025). "MYH9 mutation might disorder renal epithelial transport pathways and further result in kidney diseases." (PMID 36967395, 2023). "Interestingly, mutations in the motor domain of NM‐IIA are predictive of the development of kidney diseases in MYH9‐RD patients, whereas mutations in its tail domain have a much lower risk of renal and other complications." (PMID 35673768, 2022). "We hypothesized that in MYH9-associated kidney disease the underlying defect might be a deregulated epithelial transport pathway that triggers tubular injury–associated disease, which in turn can lead to glomerular defects in the latter stages." (PMID 33001861, 2020). "However, other groups still report statistical evidence for MYH9 association in kidney disease, and animal models have demonstrated biological relevance for MYH9 function in the kidney." (PMID 26147622, 2015). "Finally, it has been shown that ablation of MYH9 in podocytes predisposes mice to adriamycin-induced nephropathy." (PMID 24949636, 2014). "Interestingly, evidence of association at the APOL1 locus was reduced in comparison to MYH9 (Pemp<0.045) despite impressive associations previously observed with kidney disease in African Americans." (PMID 24551085, 2014). "APOL1 variants are in strong linkage disequilibrium with MYH9 variants, and it remains controversial whether MYH9 variants play a direct role in kidney disease risk." (PMID 22956460, 2013). "Our findings and other studies suggest that MYH9 may have a broader genetic risk effect on different types of kidney diseases." (PMID 23285077, 2012). "Our findings and other studies suggest that MYH9 may have a broader genetic risk effect on kidney diseases." (PMID 23285077, 2012). "MYH9 provides a plausible genetic explanation for much of this disparity as the MYH9 alleles and the haplotype most strongly associated with kidney disease are highly frequent in African Americans (allele frequencies ≈60%) and infrequent in European Americans (≤4%)." (PMID 20634883, 2010). "Initial studies described genetic variants of the MYH9 gene, but subsequent studies revealed a high linkage disequilibrium of MYH9 with APOL1, with the latter having a higher association with kidney disease." (PMID 39857298, 2025). "Myh9&10 TAL-cKO mice develop progressive kidney disease along with altered expression and localization of UMOD and loss of NKCC2, consistent with TAL cell autonomous functions for MYH9&10." (PMID 39500539, 2025). "Recent studies have shown a positive correlation between MYH9 and APOL1 polymorphisms and kidney disease." (PMID 35386255, 2022).
kidney disease (continued). "While early and predominant pathological manifestations of MYH9‐RD are hematological abnormalities, such as thrombocytopenia and platelet macrocytosis, about 25% of the patients develop late‐onset kidney disease." (PMID 35673768, 2022). "By utilizing a custom target NGS 70-gene panel and a validation cohort, we have been able to point out some of these rare variants in the MYH9, CNDP1, SOWAHB and RGMA genes relevant to renal disease in diabetic patients." (PMID 34946941, 2021). "Inducible conditional knockout (cKO) of Myh9 and Myh10 in the renal tubules of adult mice resulted in progressive kidney disease." (PMID 33001861, 2020). "Here, we used zebrafish as an in vivo model to study the consequences of gene perturbation and potential synergistic effects of APOL1 and MYH9 in kidney disease." (PMID 26147622, 2015). "In order to improve our understanding of these phenomena we have examined MYH9-related kidney disease in murine models." (PMID 23874454, 2013). "Our patient had repeatedly normal platelet count, no giant platelets, and no other extrarenal features, suggesting the MYH9 variant was not involved in his kidney disease." (PMID 40291921, 2025). "Although it was not examined here, we hypothesize the pericardial edema in the myh9b mutants is likely related to defects in kidney development based on the known role for MYH9 in human kidney disease." (PMID 39503257, 2025). "Myh9&10 TAL-cKO mice develop progressive kidney disease with pathological tubular injury confirmed by histological changes, tubular injury markers, upregulated endoplasmic reticulum (ER) stress/unfolded protein response, and higher blood urea nitrogen and serum creatinine." (PMID 39500539, 2025). "Furthermore, inducible conditional knockout of Myh9 in the renal tubules of adult mice resulted in progressive kidney disease with expansion of ER tubules and activation of ER stress." (PMID 34426759, 2021). "Adult mouse renal epithelium specific knockout of Myh9 and Myh10 genes result in kidney disease." (PMID 33001861, 2020). "Previous studies suggested that common polymorphisms in MYH9 were strongly associated with nondiabetic kidney diseases in several ethnic populations." (PMID 29862302, 2018). "The identification of MYH9 gene suggests a novel pathway of kidney disease progression." (PMID 28604601, 2017). "Furthermore, the polymorphisms of other genes such as transforming growth factor-β1 (TGF-β1), non-muscle myosin heavy chain 9 (MYH9) and apolipoprotein L1 (APOL1) have been shown in associations with kidney diseases." (PMID 27114872, 2016). "Such variable penetrance for Myh9-related kidney disease was suggested to result from the influence of additional modifying genes, which might be uncovered through congenic analysis of resistant and sensitive mouse strains." (PMID 23874454, 2013). "The two identified APOL1 risk alleles were noted to be in strong linkage disequilibrium with the MYH9 risk haplotype, and association between APOL1 and kidney disease remained significant after further adjustment for this and other combinations of the MYH9 alleles." (PMID 23782479, 2013). "In addition, human polymorphisms in MYH9 correlate with several common kidney diseases including primary focal and segmental glomerulosclerosis and hypertensive nephrosclerosis, although the causality and mechanism for these common kidney diseases remains unclear." (PMID 23874454, 2013). "Future studies will aim to uncover the mechanisms by which Myh9 functions in kidney disease." (PMID 23874454, 2013). "Polymorphisms in the MYH9 gene in relation with kidney disease have not yet been investigated in mixed ancestry African populations." (PMID 23285077, 2012). "In 2008 two studies identified single nucleotide polymorphisms (SNPs) in the MYH9 gene which conferred most of the increased risk for nondiabetic kidney disease in African Americans." (PMID 23285077, 2012).
kidney disease (continued). "Recently MYH9 gene polymorphisms have been shown to account for much of the excess risk of HIV-associated nephropathy, hypertensive, diabetic and nondiabetic kidney disease in African Americans." (PMID 21251296, 2011). "Our experiments show that conditional genetic inactivation of Myh9 and Myh10 in the TAL segment results in progressive kidney disease." (PMID 39500539, 2025). "Myh9 inactivation by itself resulted in a later onset progressive kidney disease in mice but with decreased severity and mortality (data not shown; unpublished observations)." (PMID 33001861, 2020).
infection (31 papers, 2014 to 2026). The state of being infected such as from the introduction of a foreign agent such as serum, vaccine, antigenic substance or organism. "In recent years, several studies have implicated MYH9 as a potential receptor involved in infection by viruses such as HSV-1, SFTSV, EBV, and PRRSV." (PMID 31905776, 2019). "Further studies that investigate the contribution that molecules such as MYH9 have on the infection of different ORF5 PRRSV variants are needed." (PMID 31736919, 2019). "Here, we showed that MYH9 enhances infection of endocytic viruses from divergent families, including Arenaviridae, Flaviviridae, Rhabdoviridae, and Togaviridae, and that such activity is conserved in human and mouse cells." (PMID 41217108, 2025). "Collectively, our results demonstrate that MYH9 translocates to the plasma membrane upon infection to support post-binding steps of viral endocytosis." (PMID 41217108, 2025). "MYH9 has been identified as a functional receptor for the infection of viruses, such as HSV-1 and Epstein–Barr virus." (PMID 40006922, 2025). "We found that MYH9 expression increases the infection of viruses exploiting different endocytic pathways/mechanisms to enter cells, including flavivirus, arenavirus, rhabdovirus, and togavirus, in human and mouse cells." (PMID 41217108, 2025). "Collectively, these data suggest that MYH9 is a pleiotropic proviral host factor that supports infection of viruses exploiting both DYN-2-dependent and -independent uptake mechanisms." (PMID 41217108, 2025). "By analyzing TCRV and LCMV infection, which, respectively, use CME and MPL for cell entry, we showed that MYH9 supports infection of viruses exploiting both dynamin-dependent and -independent uptake processes." (PMID 41217108, 2025). "To further characterize the role of pY in infection, we lastly sought to identify which kinase(s) phosphorylate MYH9 upon virus entry." (PMID 41217108, 2025). "As expected, the infection levels of HPV16 in HeLa-MYH9 cells were almost three-fold higher than those in HeLa cells, suggesting that the overexpression of myosin-9 in HeLa cells can enhance the infection of HPV16." (PMID 38242322, 2024). "MYH9 interacts with PRRSV glycoprotein 5 (coded for by ORF5), changing cell susceptibility to infection." (PMID 31736919, 2019). "To date, it has been reported that herpes simplex virus-1 (HSV-1), thrombocytopenia syndrome virus (SFTSV), Epstein-Barr virus (EBV), and PRRSV utilize MYH9 as a necessary factor for infection of permissive cells." (PMID 31649651, 2019). "Our previous work demonstrated that MYH9 also guides the infection process after virus particles attach to cell surface receptors, culminating in completion of subsequent un-coating events required for PRRSV genomic release within the host cell." (PMID 27686528, 2016). "The potential role of MYH9 on PRRSV infection was also investigated in vivo using a piglet model of infection." (PMID 27112594, 2016). "Additionally, MYH9 is involved in the early infection of severe fever with thrombocytopenia syndrome virus (SFTSV) in vitro, and the activation of a Rho/NM II-dependent pathway facilitates the invasion of Salmonella or fusion of Sendai virus with host cells." (PMID 40006922, 2025). "There are nine families of NRTKs in mammals, known as Src, Abl, Fes, Jak, Ack, Syk, Tec, Fak, and Csk, which could phosphorylate/activate MYH9 to promote infection." (PMID 41217108, 2025). "We found that MYH9 increases infection levels of unrelated enveloped viruses, including flavivirus, arenavirus, rhabdovirus, and togavirus, which use different mechanisms of virus entry, and that its ATPase activity and self-oligomerization are essential for its proviral activity." (PMID 41217108, 2025). "Similarly, the presence of NTHi-induced upregulation of occludin (OCLN) and MYH9 possibly improves cellular polarity as a resistance mechanism to NTHi infection." (PMID 40492732, 2025).